FABP4 (fatty acid binding protein 4)
Diseases named in the same sentence as FABP4 in open-access papers (continued):
Sharing a sentence is not in itself a finding about the gene and the disease.
breast cancer (continued). "Notably, FABP4 was detected in blood vessels and adipocytes adjacent to metastatic relapse tissue of human breast cancer patients." (PMID 38060103, 2023). "Inhibition of FABP4 can induce apoptosis of breast cancer cells." (PMID 37260987, 2023). "Additionally, CsnB also acts as a candidate to downregulate CD36/FABP4 expression, leading to the inhibition of fatty acid uptake and consequent breast cancer cell proliferation in NR4A1-dependent manner." (PMID 36052242, 2022). "Adipocytes supply fatty acids in the tumour microenvironment to provide metabolic energy and a key molecule in this process, FABP4, can influence β-oxidation in breast cancer cells, which in combination with free fatty acids (FFA) supports and promotes cancer cell survival and growth." (PMID 36532833, 2022). "Analysis of the prognostic value related to TR expression showed that patients with breast cancer with low mRNA expression levels of FABP4 (log-rank P = 0.012), ADIPOQ (log-rank P = 0.01), PPARG (log-rank P = 0.00013), and PPARGC1A (log-rank P = 0.02) had worse OS than those with high mRNA levels." (PMID 36114448, 2022). "Nonetheless, the investigators' findings are inconsistent, FABP4 is highly expressed in breast cancer and may play a key role in metastasis and stromal cell interactions." (PMID 36532833, 2022). "In the present study, we show that each of the three ligands could also reprogram CAFs and induce their transdifferentiation by overexpressing CD36 and FABP4 while strongly suppressing the growth of breast cancer cells." (PMID 36361532, 2022). "Indeed, genetic ablation or chemical inhibition of FABP4 in TAMs has been shown to suppress mammary tumour growth." (PMID 34572888, 2021). "However, inhibiting both CD36 and FABP4 significantly decreased the breast cancer cell viability over 72 h." (PMID 34561446, 2021). "Similarly, CD36 and FABP4 inhibition significantly decreased the proliferative, migratory, and invasive abilities of breast cancer cells." (PMID 34561446, 2021). "Taking all together these findings indicate that inhibiting both CD36 and FABP4 induces significant accumulation of unmetabolized lipid, resulting in apoptosis in breast cancer cells and chemical inhibitors of CD36 and FABP4 effectively reduces tumour growth in vivo." (PMID 34561446, 2021). "Previously, our group demonstrated high FABP4 circulating levels in breast cancer (BC) patients." (PMID 34503091, 2021). "In cancer, numerous reports suggest that BMA-derived fatty acids and factors such as fatty acids binding protein 4 (FABP4) and leptin, might drive tumour progression in prostate and breast cancer." (PMID 32527062, 2020). "Moreover, a recent study reported that circulating fatty acid-binding protein released by adipose tissue (A-FABP or FABP4) promotes breast cancer stemness by activating the IL-6/STAT3/ALDH1 pathway." (PMID 32913185, 2020). "However, FABP4 expression is downregulated in the fat tissue surrounding breast cancer, while circulating, FABP4 levels in plasma are increased in breast cancer patients, and exogenous FABP4 accelerates breast cancer cell proliferation." (PMID 31500658, 2019). "Furthermore, FABP4 inhibitors are in clinical development to treat breast cancer patients." (PMID 40759794, 2025). "To determine the role of the accumulated lipids in macrophages, we noticed that FABP4 expression was not only associated with the LA/CEBPα/DGAT-mediated lipid accumulation pathway, but also highly correlated with the β-AR/ATGL/HSL-mediated lipolysis pathway in breast cancer." (PMID 39513934, 2024). "Therefore, targeting circulating FABP4 represents a novel strategy for treatment of breast cancer." (PMID 39054536, 2024). "Therefore, our findings suggest FABP4 as a crucial lipid messenger that facilitates unsaturated FA-mediated lipid accumulation and lipolysis in TAMs, thus contributing to the metastasis of breast cancer." (PMID 39513934, 2024).
breast cancer (continued). "Thus, developing therapies that block the activity of the secreted FABP4 might provide a new avenue for the treatment of breast cancer." (PMID 39513934, 2024). "Moreover, FABP4 levels significantly correlated with ER status in patients with breast cancer." (PMID 36114448, 2022). "Furthermore, previous studies have identified FABP4 as a prognostic marker in breast cancer." (PMID 26959740, 2016). "In this study, we comprehensively analyzed the expression profiles of FABP4 and FABP5 in both normal and breast cancer tissues to assess their clinical significance and potential therapeutic implications." (PMID 40106183, 2025). "Among the key genes found in these enriched categories, TPSD1, FABP4, CARTPT, TRH, CSN3, and MMP9 stand out based on previously published data, which suggest their critical roles in cancer progression, including breast cancer." (PMID 40870889, 2025). "Another potential mechanism of FABP4 interaction involves the WNT signaling pathway—a key regulator of cell proliferation and differentiation that is frequently disrupted in breast cancer." (PMID 40870889, 2025). "Emerging evidence from our group and others has shown that FABP4 and FABP5 play critical roles in breast cancer development and progression in preclinical models." (PMID 40106183, 2025). "Altogether, the different expression patterns/levels of FABP4 and FABP5 in invasive breast cancer suggested their distinct roles in breast cancer development and progression." (PMID 40106183, 2025). "(C) Expression of FABP4 and CD163 was highly correlated as analyzed by the Spearman correlation analysis in breast cancer tissues." (PMID 39513934, 2024). "Analyzing the TCGA human breast cancer database, we found that compared to other FABP family members FABP4 was mostly correlated with C/EPBα, but not with other C/EBP members." (PMID 39513934, 2024). "Recent investigations have provided evidence of FABP4, CD36, and ANGPTL4, proteins involved in the release, uptake, and intracellular handling of triglycerides and fatty acids, in breast cancer pathology." (PMID 39456610, 2024). "Breast cancer cells were added to a transwell and cocultured with these different FA-or BSA-treated FABP4 WT or KO macrophages for 24 hr." (PMID 39513934, 2024). "We demonstrated a heatmap and prognostic value of DNA methylation clustering of the expression levels of FABP4, ADIPOQ, PPARG, PPARGC1A, CD36, and CREBBP in breast cancer." (PMID 36114448, 2022). "Oncoprint analysis revealed genetic alterations in FABP4 (14%), ADIPOQ (2.9%), PPARG (2.8%), PPARGC1A (1.5%), CD36 (1.7%), and CREBBP (11%) in patients with breast cancer in a TCGA study." (PMID 36114448, 2022). "DEGs Bcl3, ADGRG7, FABP4, IRF4, their regulating miRNAs and TFs have strong impact on proliferation and metastasis of breast cancer in bone tissues." (PMID 35388653, 2022). "DNA methylation analysis revealed that the predictive significance of FABP4, ADIPOQ, PPARG, PPARGC1A, CD36, and CREBBP in a specific CpG was significant in the emergence of breast cancer." (PMID 36114448, 2022). "Oncoprint analysis showed genetic alterations in FABP4 (14%), ADIPOQ (2.9%), PPARG (2.8%), PPARGC1A (1.5%), CD36 (1.7%), and CREBBP (11%) in patients with breast cancer in a TCGA study." (PMID 36114448, 2022). "Oncoprint analysis revealed genetic alterations in FABP4 (14%), ADIPOQ (2.9%), PPARG (2.8%), PPARGC1A (1.5%), CD36 (1.7%), and CREBBP (11%) in patients with breast cancer in the TCGA study." (PMID 36114448, 2022). "In breast cancer patients, increased CD36 expression occurs, with increased expression of lipid transport receptors (LDL) and FABP4." (PMID 34561446, 2021). "The adipokines plasminogen activator inhibitor 1 (PAI-1), FABP4, and secreted frizzled-related protein 5 (SFRP5) are also found in the local environment of the breast and have been shown to contribute to breast cancer progression." (PMID 34944905, 2021).
breast cancer (continued). "Next, we determined the correlation between increased CD36 expression and the various FABP genes (FABP1, FABP2, FABP3, FABP4, FABP5 and FABP6) in the TCGA breast cancer cohort." (PMID 34561446, 2021). "Perhaps the most intriguing finding from our study was that CL-TNBC, specifically, had much higher expression of CD36, LPL, PDGFRB, FABP4, and PDK4 compared to all other breast cancers, including basal-TNBC." (PMID 31942031, 2020). "Up-regulated expression of COL10A1, MMP11, CST1, GJB2, MMP1, MMP13, and CEACAM6; down-regulated expression of ADH1B, CIDEC, THRSP, GPD1, TIMP4, FABP4, and SCARA5 genes was common in breast cancers of the two populations." (PMID 31292488, 2019). "FABP4 and CD36 were scarcely expressed in breast cancer cell lines in the current study, so we focused on FABP5." (PMID 29914512, 2018). "First, the mRNA expression levels of FABP4,FABP5 and another putative FA translocase, CD36, were detected in various breast cancer cell lines." (PMID 29914512, 2018). "This was in accordance with Guaita-Esteruelas’s study in which FABP4 and CD36 were found to be rarely expressed in the breast cancer cell lines MCF-7 and MDA-MB231 when detected by western blot." (PMID 29914512, 2018). "We demonstrated that the expression of adipogenesis-related genes HOXC8, HOXC9, FABP4 and HSL in adipose tissue adjacent to malignant breast tumors was down-regulated and the level of inflammatory cytokines, like TNFα and MCP-1, was up-regulated." (PMID 25291184, 2014). "Surprisingly, the 15 breast cancer patients in our control cohort, who did not develop lymphedema within 5 years of monitoring, exhibited FABP4 levels comparable to those of healthy individuals." (PMID 40759794, 2025). "To investigate the role of FABP4 and FABP5 in breast cancer development, we first assessed their expression patterns in normal adjacent breast tissue specimens collected from patients with breast cancer." (PMID 40106183, 2025). "We also observed elevated FABP4 levels in plasma from both breast cancer-related and non-breast cancer lymphedema patients, suggesting FABP4 as a potential therapeutic target across diverse patient populations." (PMID 40759794, 2025). "We showed that the expressions of FABP4 are found in the luminal subtypes of breast cancer; nonetheless, it was not included in the most important hallmark of any subtype." (PMID 36230586, 2022). "Another study also revealed that serum FABP4 levels are elevated in obese breast cancer patients than in non-obese breast cancer patients." (PMID 35899119, 2022). "Taken together, FABP4 expression levels were not different in any subtype of breast cancer but played a critical role in the progression of ER+ and TNBC." (PMID 36114448, 2022). "In breast cancer cells, exogenous FABP4 activates the AKT and MAPK signaling cascades, while inhibiting these pathways could impair FABP4-induced breast tumor growth." (PMID 35899119, 2022). "FABP4 increases breast cancer cell proliferation in MCF-7 (luminal breast cancer) and MDA-MB-231 triple-negative breast cancer cells, but activation of fatty acid transporters only occurs in MCF-7 luminal breast cancer cells." (PMID 36114448, 2022). "There is compelling evidence that FABP4 chaperone protein and CD36/SR-B2 constitute pivotal regulatory factors of fatty acid transport in human cancer and are upregulated in several human cancers, e.g., breast cancer, colon cancer, cervical cancer." (PMID 36012230, 2022). "Thus, CD36 was inhibited, with SSO, and FABP4, with BMS309403, and their effects on breast cancer cells determined." (PMID 34561446, 2021). "It has been confirmed in many studies that FABP4 is functionally responsible for aggressive patterns of colon cancer, breast cancer, ovarian cancer, prostate cancer, and non-small-cell lung cancer." (PMID 34943506, 2021). "Among the FABP isoforms, FABP4 and FABP5 likely play critical roles in mammary tumor development." (PMID 31941087, 2020).
breast cancer (continued). "Despite consistent correlation in expression between CD36, LPL, PDK4, and FABP4 in all breast cancer subtypes (data not shown), the only subtype that displayed poorer survival was CL-TNBC (p = 0.0119; HR = 1.92)." (PMID 31942031, 2020). "Relative mRNA expression levels of FABP4, FABP5 and CD36 in breast cancer cell lines." (PMID 29914512, 2018). "We also found the association between expression of lipid metabolism-related proteins and poor prognosis in the breast cancer subtypes: HSL negativity and acyl-CoA oxidase 1 positivity in invasive breast cancer, and FABP4 positivity and CPT-1 positivity in the TNBC subgroup." (PMID 28124996, 2017). "Inhibiting the activity of FABP4 and/or FABP5 may offer a novel strategy for breast cancer therapy." (PMID 40106183, 2025). "Transplantation studies of mammary tumor cells have shown that cells transferred into WT mice have greater proliferative potential than those transplanted into FABP4−/− animals, despite tumor cells lacking FABP4 expression." (PMID 30705117, 2019). "Furthermore, CD36 in interaction with FABP4 that enhance the import of free fatty acids from adipocytes in the tumor microenvironment leads to activation of STAT3 signaling, metabolic reprogramming with a shift toward beta oxidation and promoting breast cancer progression." (PMID 39920872, 2025). "Thus, elevated levels of FABP4 and FABP5 may serve as poor prognostic markers for breast cancer." (PMID 40106183, 2025). "Moreover, in breast cancer, serum FABP4 is positively connected with tumor size and nodal-status." (PMID 35899119, 2022). "The mRNA levels of FABP4, ADIPOQ, PPARG, CD36, and PPARGC1A were significantly lower in patients with breast cancer than in those without breast cancer." (PMID 36114448, 2022). "Relapse-free survival (%RFS) indicated that FABP4 (p = 0.015) and FABP5 expression (p = 0.075) correlated with TNBC occurrence and decreased survival, but not in hormone positive mammary tumors." (PMID 31941087, 2020). "Furthermore, FABP4 is also released from these macrophages, and the expression of fatty acid-binding proteins in tumor-associated macrophages (TAM) promotes breast cancer progression, suggesting that macrophages, not adipocytes, may be the main source of FABP4 in patients with breast cancer." (PMID 31500658, 2019). "A study has shown that circulating levels of A-FABP, also known as FABP4, are significantly higher in obese patients with breast cancer than in those without breast cancer, and circulating A-FABP enhances tumor stemness and aggressiveness by activating the IL-6/STAT3/ALDH1 pathway." (PMID 37056351, 2023). "The mRNA expression levels of FABP4, ADIPOQ, PPARG, CD36, and PPARGC1A were significantly lower in patients with breast cancer, whereas the mRNA levels of CREBBP were not different between patients with breast cancer and normal breast tissues." (PMID 36114448, 2022).
ovarian carcinoma (106 papers, 2012 to 2025). A malignant neoplasm originating from the surface ovarian epithelium. "An investigation into ovarian cancer revealed that the absence of FABP4 is linked to the metastasis of ovarian cancer, and targeting FABP4 in ovarian cancer cells can impede their capacity to adapt and colonize lipid-rich tumor microenvironments." (PMID 41034734, 2025). "High expression of FABP4 is significantly associated with peritoneal metastasis, chemoresistance, and shortened patient survival in ovarian cancer." (PMID 40717587, 2025). "Inhibition of FABP4 prevented adipocyte-mediated invasion and lipid accumulation in human ovarian cancer cells in vitro, while FABP4 deficiency resulted in fewer metastatic nodules in the ovarian bursa in a mouse model of ovarian cancer." (PMID 34983949, 2022). "Knockdown of FABP4 resulted in increased 5-hydroxymethylcytosine levels in the DNA, downregulation of gene signatures associated with ovarian cancer metastasis, and reduced clonogenic cancer cell survival." (PMID 33498240, 2021). "FABP4 has been proposed as a therapeutic target, and FABP4 elevation in primary ovarian cancer tissue was significantly associated with the risk of residual disease after primary debulking surgery in patients with high-grade serous carcinoma." (PMID 34440886, 2021). "FABP4-deficient mice with ovarian cancer have reduced omental metastasis, confirming that adipocyte-derived lipids play important roles in the omental metastasis of ovarian cancer." (PMID 33926551, 2021). "FABP4 has also been associated with elevated levels of metabolites for fatty acid saturation and oxidation in ovarian cancer." (PMID 33352874, 2020). "Other studies have implicated a role for fatty acid binding protein 4 (FABP4), i.e., another hypoxia-induced lipid transport protein, in ovarian cancer metastasis." (PMID 30767150, 2019). "Increased lipid uptake regulated by the receptor CD36 and the transport protein FABP4 has been implicated in ovarian cancer metastasis." (PMID 31769430, 2019). "With RPPA and metabolite arrays, we found that FABP4 regulates pathways associated with metastasis and affects metabolic pathways in ovarian cancer cells." (PMID 30050129, 2018). "An elegant study in ovarian cancer demonstrated that coculture with adipocytes increases FABP4 protein expression and promotes migration and invasion of ovarian cancer cells, while FABP4 deficiency ameliorated the adipocyte-derived metastatic potential." (PMID 25866768, 2015). "The key factor implicated in adipocyte-tumor cell interactions in ovarian cancer is a lipid chaperone, fatty acid binding protein 4 (FABP4)." (PMID 24240026, 2013). "In addition, FABP4 represents a fundamental protein for the dialog between cancer-associated adipocytes (CAAs) and tumor cells in ovarian cancer." (PMID 37874427, 2024). "It has been shown that the knockdown of FABP4 leads to increased 5-levels of hydroxymethylcytosine in DNA, downregulation of key genes associated with ovarian cancer metastasis, and reduced survival of replication to cancer cells (Furuhashi, Saitoh, Shimamoto, & Miura, 2014)." (PMID 35646090, 2022). "Intriguingly, in a Fabp4-knockout mouse model, FABP4 deficiency impaired the metastatic progression of ovarian cancer cells in the peritoneal cavity by altering lipid availability, indicating that FABP4 is a crucial modulator of ovarian cancer metastatic progression in the omentum." (PMID 30568223, 2019). "This indicates FABP4 is involved in modulating growth and behavior of metastatic tumor cells by increasing the availability of energy-dense lipids, as shown recently in ovarian cancer cells where its upregulation was linked to activation of β-oxidation pathway." (PMID 24240026, 2013). "The upregulation of polycystic ovary-associated gene Fabp4 and ovarian cancer gene Prkcbp1 may be of particular importance." (PMID 22260314, 2012).